IL6 (interleukin 6)
Diseases named in the same sentence as IL6 in open-access papers (continued):
Sharing a sentence is not in itself a finding about the gene and the disease.
tumor (continued). "A positive feedback loop ensues whereby these cytokines, such as IL-6, IL-8, and TNF-α, amplify the inflammatory infiltrate in the tumor microenvironment and systemically." (PMID 37964946, 2023). "In particular, we previously reported the development of SC144, a small-molecule gp130 inhibitor that can block IL-6-induced nuclear translocation of STAT3, and shown their anti-tumor efficacy in murine xenograft tumor models." (PMID 37553327, 2023). "Inflammatory mediators such as TNF-α, IL-1β, IL-6, and IFN-γ promote an increase in blood supply to the tumor." (PMID 37894468, 2023). "We also found a significant positive correlation between a high amount of F. nucleatum and high levels of IL-6, and TNF-α expression in the tumor tissues." (PMID 38075864, 2023). "lncSNHG1, lncSNHG3, and lncSNHG6 have also been found to promote tumor proliferation migration and EMT processes via TGF-β or IL-6 signal pathway." (PMID 37006268, 2023). "The inhibition of IL-6 in KRAS-mutant lung cancer mouse models revealed lower pro-tumor characteristics in the TME, leading to tumor suppression." (PMID 36899885, 2023). "Fusobacterium simultaneously triggers the IL-6/p-STAT3/c-MYC signaling pathway and encourages M2-type differentiation of macrophages through a TLR4-dependent mechanism, promoting tumor growth." (PMID 36845103, 2023). "Several cell types within the TME release IL-6, activating JAK/STAT3 signaling in both tumor cells and immune cells infiltrating the tumor, promoting tumor-cell proliferation, survival, invasiveness and metastasis." (PMID 37033251, 2023). "This initially counterintuitive concept actually seems to fit with experimental data, in which IL-6 and TGFβ orchestrate an EMT-permissive tumor microenvironment and tumor metastasis and make cells more resistant to chemotherapy." (PMID 37511415, 2023). "Thus, IL‐6 may play an important role in tumour progression." (PMID 36419386, 2023). "Tumor dimensions showed positive correlations with IP-10, and MIP-1 (in aqueous and vitreous humor), while Fms-related tyrosine kinase 3 ligand (FLT3LG), IL-6, IL-8, and MCP-1 were positively correlated in vitreous humor." (PMID 37628989, 2023). "Recent studies reported that the IL-6/STAT3 signaling acted to drive proliferation, invasiveness, and metastasis of cancer cells, while strongly inhibited anti-tumor immunity." (PMID 37069669, 2023). "The authors reported an increased expression of CD80 and CD86, meaning an increase in DC maturation, a tumor-inhibiting effect (tumor volume ≈ 0 mm3), and higher levels of INF-γ, TNF-α and IL-6." (PMID 37238966, 2023). "We propose that by blocking IL-6 activity at TME, this transformation will be reversed, and the proportion of M1 will increase to hence prohibit tumor growth and development." (PMID 37124547, 2023). "Treatment of A549 tumor-bearing mice with CA (20 and 40 mg/kg) meaningfully reduced the tumor volume, decreased TNF-α, IL-6, and IL-1β, p-NF-κBp65, and increased Nrf2 and HO-1 in the comparison control group." (PMID 36978983, 2023). "Both are known to produce cytokines, such as tumor necrosis factor (TNF)-α, interleukin 1 (IL1), and interleukin 6 (IL6), which can impact GBM cell behavior and contribute to tumor growth, angiogenesis, and invasion." (PMID 37345035, 2023). "A decrease in IL-6 promotes macrophage polarization and subsequently lowers STAT3 activity, thereby reducing tumor development in cancer-prone mice fed with inositol diet." (PMID 37194070, 2023). "The tumor upregulated pro-inflammatory cytokines TNF-α, MCP-1, and IL-6 when compared with the sham group." (PMID 37174010, 2023). "Macrophages can secrete a variety of cytokines, such as CXCL1, IL6, TGF-β, and VEGF, which can promote tumor growth and metastasis and increase the density of macrophages in the intratumoral region of GC patients." (PMID 36983741, 2023).
tumor (continued). "In the tumor microenvironment, continuous stimulation with IL-6 can activate JAK2, resulting in STAT3 phosphorylation and thereby promoting tumor growth, drug resistance, and metastasis." (PMID 37817809, 2023). "Table 3shows the tumor volume and plasma levels of TF, PAI-1, IL-6, and MMP-2 on day 21 in UTR mice and water-treated or EDX-treated Colon26-inoculated mice." (PMID 36751299, 2023). "Activation of inflammatory responses releases various growth factors (GFs) and pro-inflammatory cytokines, such as interleukin-6 (IL-6), interleukin-1 (IL-1), and tumor necrosis factor-α (TNF-α), altering catabolism in tumor patients." (PMID 36874094, 2023). "To evaluate the effect of ZQD on IL6/STAT3 signaling pathway, we measured cytokines and STAT3 phosphorylation in PC3 xenograft tumor." (PMID 37576403, 2023). "Consistent with the literature, we observed that UA downregulated elevated IL-6, IL-1β, and TNF-α levels in the serum of LLC tumor-bearing mice and inhibited elevated phosphorylation of NF-κB and STAT3." (PMID 37190306, 2023). "Tumor cells and tumor associated fibroblasts can secrete leukemia inhibitory factor (LIF) and interleukin‐6 (IL‐6) to promote ECM remodeling and provide conditions for tumor cell migration." (PMID 36560848, 2023). "It was also shown that IL-6, IL-8, IP-10, MCP-1, MIP-1α, MIP-1β, TNF-α, RANTES, GCSF, IFN-γ, and VEGF concentrations positively correlate with tumor size." (PMID 37628989, 2023). "Interestingly, positive correlations between CD8 and VEGF, as well as IL-6, were observed only in NR patients, indicating pathways involved in tumor growth in CC and T-cell infiltration and differentiation, which may collaborate with higher levels of CD8+ TILs in NR patients." (PMID 38114557, 2023). "Both mCAF and SPP1+ TAMs were mainly enriched in tumor tissues, and in many identical cancer hallmarks, such as EMT, angiogenesis, TGF-β, IL-6/JAK-STAT3, and TNF-α/NF-κB signaling pathways." (PMID 37853464, 2023). "Levels of the critical tumor-promoting TNF and IL-6 sera were low, but mucosal-healing IL-22 also supports tumor formation." (PMID 37275854, 2023). "It has previously been reported that IL-6, a soluble factor present in MDCS, enhances tumor proliferation in SBC-3 cells." (PMID 36961655, 2023). "CAFs also release IL-6, IL-1, VEGF, and CCL2, which suppress anti-tumor immunity and promote the formation of Tregs, which are immunosuppressive." (PMID 37795038, 2023). "Many stimuli have been reported in previous literature, including IFN-γ and GM-CSF, which induce neutrophils to N1 polarization for anti-tumor function, and IL-6, IL-8, CXCL2, and CXCL5, which induce neutrophils to N2 polarization for pro-tumor function." (PMID 37063892, 2023). "In a CRC model, joint IL-6 and GM-CSF blockade dramatically reverses TAM infiltration, which generates an immunosuppressive tumor niche, and metastasis in orthotopically co-implanted CAFs and CRC cells in vivo." (PMID 37046676, 2023). "Obese ADFs attract CD3+ T-lymphocytes and F4/80+ macrophages and increase the expression of chemotactic factors IL-6, MIP-2, and MCP-1 when cultured with tumor cells." (PMID 37046676, 2023). "These cytokines, such as IL-6, IL-17, and TNF-α, directly promote tumorigenesis, tumor cell proliferation, angiogenesis, metastasis, and cell death." (PMID 38075864, 2023). "The most basic physiological difference between normal and tumor tissue is that many chemokines and cytokines are induced by hypoxia such as TNF-α, InterLeukin 6, and InterLeukin-1 α and β." (PMID 37298889, 2023).
tumor (continued). "Blocking cytokines secreted by CAFs (such as IL-6, IL-8, IL-10 and TGF-β) combined with PD-1/PD-L1 can improve the anti-tumor immune response through increasing T cell infiltration and alleviating the role of PD-1 in inhibiting T cell activity." (PMID 37064113, 2023). "While these data would be consistent with IL-23R pathway activation in tumor tissue, STAT3 activation can also be mediated by IL-6 or IL-10." (PMID 38375204, 2023). "Consistently, Rh4 reduced the expression levels of HDAC4, IL-6 and p-STAT3 in tumor tissues of nude mice intratumorally injected with LPS as comparison to the LPS group." (PMID 37843550, 2023). "Of other cytokines, tumour necrosis percentage positively correlated with IL7 in Cohort 2B but not in 2 A (beta = 0.190 and 0.083, P = 0.017 and 0.375, respectively), and with IL6 in Cohort 2A (beta = 0.191, P = 0.043)." (PMID 37031328, 2023). "Tumor cells secrete cytokines such as VEGF, TGF-β, IL-6, and Macrophage Colony-Stimulating Factor (MCSF), which increase angiogenesis, promote suppressor cell migration to the tumor site and inhibit the specific CTL response." (PMID 38137888, 2023). "Among interleukin-mediated signaling pathways, IL6 and IL2 are established inflammatory factors involved in tumor immunity regulation by facilitating lymphocyte growth and function." (PMID 36759763, 2023). "Previous studies have shown that the IL-6-JAK-STAT3 signaling pathway is abnormally over-activated in patients with hematopoietic malignancies or solid tumors, to encourage tumor cell proliferation, survival, invasion, and metastasis." (PMID 37251370, 2023). "This occurs through the activation of interleukin-6 (IL-6) autocrine signaling and the phosphorylation of the STAT3 signaling pathway, consequently expediting tumor growth." (PMID 38087360, 2023). "Therapeutic targeting of IL-6 or progranulin via their common receptor, sortilin, could be a potential novel treatment strategy for cancer forms with high levels of IL-6 or progranulin, inhibiting cancer stem cell functions and consequently reducing tumor aggressiveness and metastasis formation." (PMID 38136303, 2023). "The gray intensity analysis showed that three cytokines, IL-6, IL-8, and CCL18, were abundant in the chemoresistant tumor samples with plentiful CD10+GPR77+ CAFs, which were validated by ELISA." (PMID 36418470, 2023). "Mesenchymal stem cells (MSCs) recruited from the bone marrow can differentiate into a subpopulation of CAFs under tumor-derived TGF-β, WNT, and IL-6/STAT3 signaling." (PMID 37394578, 2023). "There was a positive correlation between IL-6 (r = 0,832; p-value = 0,000), CA-125 (r = 0,716; p-value = 0,000), or HE4 (r = 0,716; p-value = 0,000) with tumor resectability." (PMID 37792745, 2023). "Combined IL-6 and CTLA-4 blockade supports Th1 cytokines that crosstalk to facilitate chemokine production from tumor cells." (PMID 36881480, 2023). "Through the IL-6/STAT3/PD-L1 axis, CAFs modulated neutrophil activation, survival and function in tumour tissues in HCC to promote immune suppression." (PMID 37569598, 2023). "After therapy, there was a considerable rise in immune cytokines TNF-α, IL-6, and IFN-γ in peripheral blood serum, as well as a robust infiltration of CD8+ T cells at primary and distant tumor sites, resulting in systemic therapeutic antitumor effects." (PMID 36987269, 2023). "Additionally, CAFs may favour a pro-tumour environment by paracrine secretion of E2 and IL-6." (PMID 38332913, 2023). "MSCs have also been shown to promote tumor angiogenesis through release of VEGF, bFGF, FGF-2, IL-8, IL-6, TNF, IGF-1 and TGF β as well as subsequent transformation into smooth muscle cells and pericytes, coupled with formation of new tumor vessels." (PMID 36926687, 2023). "The IL-6/JAK/STAT3 signaling pathway drives the metastasis, proliferation, survival, and invasiveness of tumor cells in the tumor microenvironment by suppressing the antitumor immune response." (PMID 37176567, 2023).
tumor (continued). "Glucose-depleted CAFs take up lactate for use as an energy source and further produce IL-6, leading to the formation of an immunosuppressive TME in synergy with lactate and promoting tumor progression." (PMID 37733442, 2023). "Treatment of pancreatic CAFs with all-trans retinoic acid (ATRA) reduces expression of αSMA and FAP, decreases the production of ECM, reduces the expression and secretion of IL-6, and results in CAF-mediated reduction of migration and EMT in the tumor cells." (PMID 37046676, 2023). "Activation of these cells produces pro-thrombotic and pro-tumorigenic TF and activates STAT3-mediated IL-6, PAI-1, and MMP-2 production (black upward arrows), and RAS/PI3K/SyK/Ki67/cyclin D1 signaling pathways, leading to tumor growth." (PMID 36751299, 2023). "Even though, the composition of SASP varies depending on the cell and tissue of origin, the inflammatory cytokines IL-6 and IL-8 are consistently present and are responsible for maintaining and propagating the SASP response in the tumour microenvironment." (PMID 37047661, 2023). "RMS-high group was related to worse prognosis, which was partly attributed to significant activation of EMT, Notch, IL-2/STAT5, IL-6/JAK/STAT3, angiogenesis signaling pathways, which was instrumental in tumor invasion." (PMID 37124622, 2023). "In turn, enhanced osteoblast activity drives tumor progression by releasing insulin-like growth factor (IGF-1), IL-6, and IL-8." (PMID 37345069, 2023). "Longitudinal BLI data indicated CD4+ T cell–dependent efficacy of combined IL-6 and CTLA-4 blockade, as CD4+ T cell–depleted mice receiving therapeutic Abs had accelerated tumor growth progression compared with mice receiving only the combination therapy." (PMID 36881480, 2023). "In this study, we found that diHEP-DPA significantly inhibited the infiltration of TAMs and decreased the secretion of MMP2, MMP9, VEGF, IL-6, and TNF-α in tumor tissue." (PMID 36827121, 2023). "Recent data showed that the blockage of the IL-6/STAT3 pathway results in the activation of apoptosis, thus suggesting that new regulators of STAT3 in tumours are important targets for potential therapeutic strategies in the treatment of cancer." (PMID 37298475, 2023). "During tumor progression, CAAs support CRC onco-inflammatory milieu through release of proinflammatory cytokines, including IL1-β, IL-6, IL-8, and TNF-α that modulate the innate and adaptive immune response." (PMID 37760840, 2023). "For example, interleukin 6 (IL-6) is an important STAT3 activator and a major mediator of inflammation that acts on tumor cells to induce the expression of STAT3 target genes." (PMID 37242454, 2023). "These extracellular microparticles are able to fuse with cancer and normal lung cells and inhibit tumor cell migration, as well as reduce inflammation in the tumor microenvironment by decreasing the release of S100A8/A9 and IL-6." (PMID 36670988, 2023). "Within the tumor microenvironment, TAMs secrete IL4, IL-5, and IL-6, which cannot only facilitate invasion and metastasis, but also promote tumorigenesis, angiogenesis, matrix remodeling, and immune system suppression." (PMID 36979391, 2023). "Levels of Inflammatory cytokines such as IL-6, MCP-1, and TNF-α were altered in serum, but increased TNF-α and NOS in tumor tissues was observed, even more so when augmented with nitroglycerin." (PMID 37514190, 2023). "For instance, myokines with tumour-suppressing features such as SPARC, Decorin, IL-6, and Irisin have been revealed that are also involved in the prevention of muscle atrophy and sarcopenia alleviation." (PMID 38136400, 2023). "Another STING agonist, SHR1032, is tumor protective in murine CRC by stimulating the type 1 IFNs, TNF-α, and IL-6 release in the TME." (PMID 37380989, 2023).
tumor (continued). "In this space, cytokines and chemokines such as TGFβ1, IL-6, IL-6Rα and IL-8 (CXCL8) drive the tumor toward an aggressive mesenchymal state, while IL-10, IL-1RA and TGFβ1 actively suppress expression of immune effector functions." (PMID 37063842, 2023). "This last subpopulation can produce several factors such as IL-33, IL-6, IL-8, and CXCL12, which in turn promote tumor angiogenesis and provide chemoresistance and resistance to the T-cell killing effect." (PMID 37511856, 2023). "IL‐10 induces the TAM M2 polarization that further secrete high IL‐10, IL‐6, TGF‐β, which can promoting fibrosis and enhance tumor growth." (PMID 36816959, 2023). "IL-17-induced inflammatory mediators, such as IL-1β, IL-6, and TGF-β, promote a proangiogenic and immune suppressive tumor environment that enhances tumor growth." (PMID 37631976, 2023). "M2 macrophages have shown to secrete interleukin-6 (IL-6), promoting the phosphorylation of Phosphoglycerate Kinase 1 (PGK1) in tumor cells mediated by 3-phosphoinositide-dependent protein kinase 1 (PDPK1)." (PMID 37298093, 2023). "For example, splenic stromal cells of tumor-bearing mice induce LSK cell functional alteration to generate immunosuppressive MICs via soluble factors, including IL-6." (PMID 37380989, 2023). "Longitudinal BLI indicated significant delay of tumor growth in mice receiving combined IL-6 and CTLA-4 blockade as compared with isotype control (p=0.002) or single agent (P = 0.017 versus α–IL-6; P = 0.09 versus α–CTLA-4)." (PMID 36881480, 2023). "IL-6 also upregulates cell programmed death 1 (PD-1) expression on CD8 T cells and cell programmed death 1 ligand 1 (PD-L1) on tumor cells, which leads to cytotoxic cell dysfunctionality." (PMID 38455361, 2023). "Metastasis cancer-1 and -2 subsets also shared common activated immune-related pathways (e.g., TGF-β, IL-6/JAK-STAT3, and TNF-α/NF-κB) that are closely related to EMT occurrence, tumor invasion, and metastasis." (PMID 37853464, 2023). "The release of cytokines IL-1β, IL-6, IL-8, and TNF-α was analyzed in the supernatants of tumor cells (24 h) and CD34+ HSCPs (24, 48, 72 h) after IR (single-dose: 9 Gy) in order to investigate the influence of IEPA on inflammatory responses." (PMID 36903253, 2023). "Mast cells through releasing IL-1, IL-4, IL-6, and TNF-α can actively participate in the elimination of tumor cells and rejection of tumors." (PMID 36793597, 2023). "B1R also regulated the production of the protumorigenic cytokines and chemokines IL-6, IL-8, CXCL11, and CCL5 in GBM, which contributed to tumor progression." (PMID 37627528, 2023). "High serum levels of proinflammatory cytokines, such as interleukin (IL)-1, IL-6, IL-8, and TNF-α, are often related to tumor growth and poor clinical prognosis in cancer patients." (PMID 36793738, 2023). "Tregs were recognized as a subset of T cells that suppresses immunity in sterilization and anti-tumor, thus SRPX and IL6 can be a novel target for recovering immune response in EC tumor cells." (PMID 36675190, 2023). "Proinflammatory cytokines such as IL-6, IL-8, and TNF-α have previously been shown to promote tumor initiation and progression, and expression of these cytokines is associated with a poor clinical prognosis." (PMID 36816953, 2023). "On the negative side, expanded PIT also secrete cytokines that can promote tumor EMT, including sIL-6Rα, IL-8 and IL-6." (PMID 37063842, 2023). "Specifically, they induce immunosuppression by upregulating pro-inflammatory cytokines such as IL-6 and TNF-α in lymph nodes, inhibiting tumor immune responses." (PMID 38087360, 2023). "Among them, a large number of studies have shown that IL-6 can activate the JAK/STAT pathway, induce tumor proliferation, and can also intensify endothelial-mesenchymal transition and other cancer-promoting processes." (PMID 37673886, 2023).